IL6 (interleukin 6)
Diseases named in the same sentence as IL6 in open-access papers (continued):
Sharing a sentence is not in itself a finding about the gene and the disease.
cancer (continued). "Moreover, inflammation frequently occurs during cancer progression, and indomethacin (IND) can alleviate inflammation by reducing factors such as interleukin 6 (IL‐6) and can work with DOX to enhance its antitumor properties, thereby increasing the overall effectiveness of treatment." (PMID 39545088, 2024). "Moreover, IL-6/JAK/STAT3 signaling up-regulates downstream target genes with anti-apoptotic and proliferative effects, promotes plasticity, invasion, and metastasis of cancer cells and angiogenesis, and induces cancer resistance." (PMID 37507626, 2024). "IL-6 plays a critical role in immune regulation by promoting a chronic inflammatory environment and controlling NOTCH activation, a pathway responsible for intestinal stem cell self-renewal, cancer stem cell maintenance, TGF-induced EMT, and therapy resistance." (PMID 39061234, 2024). "The reduction in IL-6 levels suggests a potential decrease in the immunosuppressive environment, which could further support the antitumor activity of TNF-α by promoting a more effective immune response against cancer cells." (PMID 39120359, 2024). "In this study, the expression of IL-6, 8, and 10 were significantly higher in the MDA-MB 231 cells treated with live P. acidilactici and its CFS than in the untreated cells, indicating that exposure of the cancer cells to bacteria triggered inflammatory responses that promote cancer progression." (PMID 38314029, 2024). "Furthermore, we identified several significantly upregulated genes (CD46, JAG1, IL6, and IL6R) that may positively correlate with cancer cells' survival and invasive capabilities in this subtype." (PMID 38571938, 2024). "In parallel with considerable overproduction of other pro-inflammatory modulators, such as TNFα, IL-2, IL-6, MIG (CXCL9), MIP-1β (CCL4) and MIP-2 (CXCL2), we also detected a significantly lower secretion of IL-10 by tILC2s that contradicted the conventional ILC2 role in cancer." (PMID 38524132, 2024). "Therefore, the increased expression of IL6 and CCL20 in response to AFB1 may play a role in AFB1-related inflammatory diseases and cancers." (PMID 38468450, 2024). "Notably, IL-6 and IL-8 were reported to predict which patients with cancer would not benefit from ICI treatment." (PMID 39200295, 2024). "This polarization leads to an augmented secretion of IL-6, which furthers migration and invasion capabilities of OSCC cells via the activation of the NF-κB/IL-6 signaling axis, highlighting a critical mechanism through which pro-inflammatory M1 TAM signals contribute to cancer aggressiveness." (PMID 39286635, 2024). "However, factors like IL-6 produced by CSCs can facilitate the dedifferentiation of non-stem cell cancer cells." (PMID 39184916, 2024). "However, we observed a relatively high transcript count for these proteins in both cancer samples and non-neoplastic tissue, suggesting the presence of cells capable of IL-6-mediated signaling in both healthy and pathologic mucosa." (PMID 38979413, 2024). "Additionally, we found that ANXA9 could transfer the S100A4 out of cancer cells and down regulation of ANXA9 could decreased the cytokines of IL-6, IL-8, CCL2, and CCL5." (PMID 38609357, 2024). "A work that investigates the role of interleukin-6 (IL-6) in cancer growth and bone metastases, concentrating on its interaction with the bone marrow microenvironment reported that bone marrow stromal cells (BMSC) generate IL-6, which activates osteoclasts and leads to bone resorption." (PMID 39125732, 2024). "Moreover, specific DCN knockdown in breast fibroblasts modulated the expression/secretion of several CAF biomarkers and cancer-promoting proteins (α-SMA, FAP- α, SDF-1 and IL-6) and enhanced the invasion/proliferation abilities of these cells through activation of the STAT3/AUF1 signaling." (PMID 38667295, 2024).
cancer (continued). "Furthermore, the same cancer cells activated with PMA showed a significant increase of IL-6 mRNA, whereas pretreatment with GNP prior to PMA stimulation dose-dependently downregulated IL-6 mRNA (p < 0.05)." (PMID 38338683, 2024). "Thus, IL-6 and TNF-α are being investigated in clinical trials for pancreatic and other cancers." (PMID 38390872, 2024). "The earlier investigations highlighted the importance of IL-6 in cytokine-mediated communication between NOFs and OPSCC cells, and our initial aims were to determine if tonsil-derived fibroblasts, both normal and cancer-derived would behave in a similar manner." (PMID 38803348, 2024). "In addition to DAMPs, ICD inducers may promote the secretion of inflammatory cytokines such as IL6 and CXCL8 (IL8) from cancer cells." (PMID 39759512, 2024). "Like other cytotoxic cancer therapies, immunotherapy promotes inflammation within the TME, which can include cytokine release syndrome characterized by hypersecretion of pro-inflammatory cytokines, including IL-6, IL-1, TNFα, IL-5, IL-10, IFN, and TGFs by various immune cells." (PMID 38330013, 2024). "Additionally, IL-6 can activate the mitogen-activated protein kinase (MAPK), phosphoinositide 3-kinase (PI3K), and activator protein-1 (AP-1) pathways, which contribute to the proliferation and survival of cancer cells." (PMID 38671854, 2024). "IL-6, as an essential trigger of epithelial-to-mesenchymal transition, activates STAT3, followed by transcription of ZEB1 and production of mesenchymal-like proteins and a mesenchymal phenotype, which is utilized by carcinoma cells to promote invasion, angiogenesis, metastasis, and apoptosis." (PMID 38541074, 2024). "This study investigated whether plasma CRP, IL‐6 and YKL‐40 had diagnostic value in 753 patients referred with nonspecific signs and symptoms of cancer to a diagnostic outpatient clinic." (PMID 36440611, 2023). "It is also known that IL-6 binds to its receptors forms a complex that activates the STAT3; thus, the STAT3 is phosphorylated via the JAK, and this activation is preferred by the PKM2, which leads to the promotion of serine hydroxymethyltransferase 2 transcription in cancer." (PMID 37514090, 2023). "TNF was significantly hypomethylated in 15 cancers, IL6 was significantly hypomethylated in 14 cancers, and BMP4 was significantly hypermethylated in 12 cancers, indicating that these important genes were regarded in a stably consistent manner among different types of cancer." (PMID 36945884, 2023). "However, anti-IL-6 alone has no significant efficacy in many aggressive cancers, including multiple myeloma, metastatic renal cell carcinoma, prostate cancer and non-small cell lung cancer." (PMID 37108179, 2023). "Additionally, the TAMs have been found to secrete IL-6, which can stimulate the transformation of non-stem cancer cells into CSCs by activating the JAK/STAT pathway." (PMID 37525217, 2023). "There was a decrease in DDIT3 expression (DDIT3 = 1.56 ± 1.0 vs. 0.89 ± 0.25 for the control group and the cancer group, respectively, p = 0.01) and no change in IL-6 expression between the control group and cancer group sera mixtures (IL6= 0.51 ± 0.19 vs. 0.55 ± 0.20, p = 0.7)." (PMID 36980729, 2023). "Interestingly, IL-6 targeting by antibodies was found to induce synergistic T cell killing effects when combined with T cell immunoglobulin and mucin-domain containing-3, also known as HAVCR2 receptor (TIM-3/ HAVCR2) therapy, in animal cancer models." (PMID 36980527, 2023). "Moreover, TIF1-γ-DM chronic exposure to IL-6 and IFN-γ could further the initiation and progression of cancer." (PMID 36357631, 2023). "The levels of TNFα, IL-1β, IL-6, and IL-12 were not affected by the cancer cell spheroids." (PMID 37445941, 2023). "The decrease in IL-6 secretion by the adipocytes upon inhibition of SHP2, PDHA1 or ROS also suggests that the SHP2-PDHA1-ROS axis might regulate inflammation in the adipose tissue, and thereby indirectly influences cancer progression." (PMID 36074246, 2023).
cancer (continued). "Furthermore, IL-6 and IL-8 are major cytokines in the TME that regulate multiple signaling pathways, including apoptosis, survival, proliferation, angiogenesis, invasiveness, migration, and metastasis, in various malignant tumors." (PMID 37627528, 2023). "In the pathway analysis, we found that PANoptosis score was positively correlated with IL6-JAK-STAT3 signaling, interferon-gamma response, inflammatory response, IL2-STAT5 signaling, and TNF-a signaling via the NF-kB signaling pathway in 33 diverse cancer types." (PMID 36890219, 2023). "M1-M2 macrophages produce a high quantity of inflammatory cytokines such as IL-1, IL-6, and TNF-alpha that in turn stimulate the further recruitment of other macrophages and concomitantly increase the aspecific response in site of the adaptive anti-cancer immune response." (PMID 36900413, 2023). "Interestingly, systematic evaluation of IL-6 can also result in a fluctuation of RDW, as an increase or decrease in RDW was closely correlated with high or low levels of IL-6, although not in the cancer background." (PMID 36814297, 2023). "Nonetheless, how IL-6 influences the responses of cancer cells to svLAAOs has not been addressed." (PMID 37385076, 2023). "Therefore, anti-TIF1-γ antibodies, VEGF-A, TNF-α, CCL2, IL6, and IFN-γ could have essential roles in indicating the presence of cancer in anti-TIF1-γ antibody-positive DM patients." (PMID 36357631, 2023). "Thus, activation of the IL-6/JAK/STAT pathway, related to SARS-CoV-2 infection and some cancers, may play an important role in oncogenesis." (PMID 37753372, 2023). "Moreover, a high level of IL-6 can favour humoral immune response T-Helper-2 (Th2), which does not contribute to combating cancer." (PMID 37047238, 2023). "Therefore, we hypothesized that VEGF-A, TNF-α, CCL2, IL-6, and IFN-γ could distinguish cancer among anti-TIF1-γ antibody-positive DM patients." (PMID 36357631, 2023). "Indeed, both TGFβ1 and IL6 have been shown to promote EMT and cancer cells metastatic potential." (PMID 36936987, 2023). "In addition, plasma levels of IL-6 and IFN-γ could differentiate cancer presence among anti-TIF1-γ antibody-positive DM patients." (PMID 36357631, 2023). "Moreover, the xenograft tumors created from the cancer cells treated with SP showed a higher level of pro-inflammatory cytokines (IL-4β, IL-6, IL-8, IL-11, IL-12, TNF-α, and transforming growth factor β [TGF-β]) compared with those generated from cancer cells treated with PBS." (PMID 36685035, 2023). "Therefore, IL6 not only regulates the cellular immune response, but also activates a vast array of signaling pathways in different cell types in the TME that facilitate cancer development." (PMID 37062842, 2023). "We therefore tested the hypothesis that elevated plasma CRP, IL‐6 and YKL‐40, alone and as a combined biomarker score, could identify groups of patients with nonspecific signs and symptoms of cancer, with high cancer risk and poor survival." (PMID 36440611, 2023). "STAT3 is a transcription factor oncogene involved in the IL-6-JAK-STAT3 signaling cascade that mediates gene expression in response to cell stimuli and thus plays a central role in cell growth and apoptosis across multiple cancers, and their targeting has shown therapeutic benefits." (PMID 37746266, 2023). "Interestingly, the IL-6/JAK/STAT3 and complement pathways were the most highly upregulated genes in Group 2, inferring an association with immune activation and cancer metastasis control, which is not reported in the BL2 subtype." (PMID 37334114, 2023). "However, we detected robust IL‐6 levels in multicellular 3D cultures throughout all treatment groups, implicating that IL‐6 is primarily not secreted by cancer cells alone." (PMID 36417691, 2023). "We investigated whether CRP, IL‐6 and YKL‐40 had diagnostic and prognostic value in patients referred with nonspecific signs and symptoms of cancer." (PMID 36440611, 2023).
cancer (continued). "Moreover, the IL-6 cytokine secreted by adipocytes plays a crucial role in the inhibition of mitochondria-triggered apoptosis in chemoresistant ovarian cancer stem cells (CSCs), particularly in the CD44+/MyD88+ cancer cell population." (PMID 38201468, 2023). "In addition, a series of experiments conducted with IL-6 and IL-6 antibodies revealed that IL-6 induces cell proliferation, migration, and invasion; however, IL-6 antibodies do not affect cancer cells." (PMID 37958980, 2023). "Likewise, the activation of NF-κB by oxLDL/LOX-1-ROS could induce the secretion of IL-6 observed in our study, which in turn may act in an autocrine fashion to stimulate STAT3 signaling, as it has been observed in other types of cancer." (PMID 36982155, 2023). "We determined the cut-off values, sensitivities, and specificities of VEGF-A, TNF-α, CCL2, IL-6, and IFN-γ as biomarkers to investigate whether their plasma levels could distinguish cancer in anti-TIF1-γ antibody-positive DM patients and reflect the presence of cancer through the ROC curves." (PMID 36357631, 2023). "Therefore, it is an index that indirectly indicates the presence of systemic metabolic abnormality derived from circulating IL-6 in cancer patients, independent of the clinical stage of cancer." (PMID 35204642, 2022). "Thus, the development of inhibitors or neutralizing antibodies targeting IL-6, IDO, GM-CSF, and STAT3 may lead to a new cancer immunotherapeutic approach that can induce tumor immune evasion of CAFs via the cell network in the TME." (PMID 35464435, 2022). "Besides studies demonstrating consistently an increased risk of mortality due to inflammation and subsequent cancer development, both CRP and IL-6 have also been shown to be associated with non-cardiovascular mortality." (PMID 36742002, 2022). "In one study, a water JCo extract inactivated the PI3K–Akt pathway in cancer cells, and our data revealed that JCo extract suppressed NFκB expression and the downstream expression of chemokines and cytokines such as TNF‐α, IL‐1β, IL‐6, and CCL2 in the rat renal cell line NRK‐52E." (PMID 36249972, 2022). "In addition, we found that Nrf2 has no obvious effect on the expression of IL-6 in senescent cancer cells, further suggesting that Nrf2-regulated cytokine expression is cell context-dependent." (PMID 35190529, 2022). "Therefore, cancer cells that do not express IL-6 or mIL-6R can still respond to IL-6 if IL-6 and sIL-6 are produced by stromal cells." (PMID 36551971, 2022). "Specific evidence for IL-6 rs1800797 and cancer-related pain is not available in literature." (PMID 35335997, 2022). "Moreover, few reports have suggested that interaction of cancer cells with macrophages induces IL-6 expression, however the mechanism by which cancer cells regulate IL-6 expression in TAMs is not well defined." (PMID 35300689, 2022). "For example, IL-34 can enhance migration and proliferation of CRC cells through ERK1/2 and MAP pathways, cancer cells’ proliferation, and migration by CAFs using netrin-1 and b-FGF induction, but also CRC cells’ diffusion and growth by stimulating TAMs to produce IL-6." (PMID 35884974, 2022). "Thus, we comprehensively measured representative inflammatory mediators, including IL-1β, IL-6, IL-10, IL-12p70, TNF, PGE2, and VEGF concentrations in the saliva of patients with cancer, which is convenient to measure, less invasive to collect, and can be done repeatedly." (PMID 35476641, 2022). "In addition, CRP may mediate carcinogenesis and cancer progression via activation of the FcgRs/MAPK/ERK, FcgRs/NF-κB/NLRP3, and FcgRs/IL-6/AKT/STAT3 pathways." (PMID 35847918, 2022). "Furthermore, when various cytokines that contribute to cancer cachexia—such as TGF‐β, IL‐6, and tumor necrosis factor alpha (TNF‐alpha)—are inhibited, bone mineral density loss is attenuated, most likely by preventing full differentiation of osteoclasts through the RANK–RANKL pathway." (PMID 34791809, 2022).
cancer (continued). "Due to the role of STAT-3 in cancer initiation and development, multiple treatments aim to inhibit the IL-6/IL-6R/STAT-3 signaling pathway, one of these treatments is tocilizumab (Tcz), a humanized monoclonal antibody that binds to membrane-bound and soluble IL-6R to inhibit IL-6 signaling." (PMID 35703345, 2022). "Moreover, some research also suggested that an imbalance of cytokines can induce brain damage i.e., the number of proinflammatory cytokines like interleukin-6 (IL-6), interleukin-8 (IL-8), and tumor necrosis factors (TNC) are significantly increased after therapy for malignant tumors." (PMID 35268306, 2022). "This liposome-based dual-blockade cancer cell immune checkpoint therapeutic strategy effectively activated anticancer T cells and nature killer (NK) cells, and promoted the release of cytokines such as interferon-γ (IFN-γ) and interleukin-6 (IL-6), which exhibit good anticancer abilities." (PMID 35524277, 2022). "Additionally, IL-6 plays a role in a variety of other processes such as metabolism, but its complete role in cancer immunology is not fully characterized." (PMID 35954360, 2022). "Therefore, the blockade of IFNs, TNF-α, IL-6, and IL17 may be a useful therapeutic approach to modulate the severity burden of cancer patients." (PMID 36550571, 2022). "Interleukin (IL)-6 family cytokines, such as IL-6 and IL-11, are defined by the shared use of the gp130 receptor for the downstream activation of STAT3 signaling and the activation of genes which contribute to the “hallmarks of cancer”, including proliferation, survival, invasion and metastasis." (PMID 35053592, 2022). "In addition, the activation of inflammatory interleukins, such as IL-1 and IL-6, and the overexpression of membrane proteins, such as MAP17, play an important role in the development of chronic inflammation and its potential progression to cancer." (PMID 36232966, 2022). "Moreover, high expression of IL-6 led to over-expression of PD-L1 in CRPC cells, which, in turn, resulted in the death or inactivation of T cells and decreased expression of the NKG2D ligand, which disrupted NK cells in recognizing cancer cells." (PMID 36230984, 2022). "Using The Cancer Genome Atlas Lung Squamous Cell Carcinoma database, several genes are highly expressed in cases with PDPN‐expressing CAFs, including interleukin (IL)‐1A, IL‐1B, IL‐6, IL‐10, CCL2, colony‐stimulating factor 1 (CSF1), FGF2, galectin 1, PDGFA, PDGFB and TGF‐β1." (PMID 35603909, 2022). "Regardless of cancer type, only IL-6 concentration significantly increased in the post-index group." (PMID 35476641, 2022). "The proinflammatory cytokine IL-6 is commonly upregulated in various types of cancer including OSCC 44, and the elevated IL-6 level may promote nodal and distant metastasis by activating the PI3K/AKT/mTOR signaling pathway and correlate with cancer proliferation and poor survival." (PMID 36046647, 2022). "Salivary IL-6, as a pro-inflammatory cytokine, activates Janus kinases (JAK) and signal transducers and activators of transcription (STATs), which stimulate mitogen-activated protein kinase (MAPK), which activates cell proliferation and angiogenesis and supports cancer development." (PMID 36005252, 2022). "In a study of patients with advanced-stage cancers, supplementation with Ganopoly, the polysaccharides fractions extracted from G. lucidum, for 12 weeks resulted in significant enhancement of cellular immunity (elevated IL2, IL6 and interferon γ in 80% of patients." (PMID 36497414, 2022). "During HP infection, the expression of IL6 in the gastric mucosa was upregulated, and IL6 can promote the activation of signal transducer and activator of transcription 3 (STAT3), which is closely related to the occurrence, development, and metastasis of malignant tumors." (PMID 35958524, 2022).